AVIL (advillin)
Description:
Ca(2+)-regulated actin-binding protein which plays an important role in actin bundling. May have a unique function in the morphogenesis of neuronal cells which form ganglia. Required for SREC1-mediated regulation of neurite-like outgrowth. Plays a role in regenerative sensory axon outgrowth and remodeling processes after peripheral injury in neonates. Involved in the formation of long fine actin-containing filopodia-like structures in fibroblast. Plays a role in ciliogenesis. In podocytes, controls lamellipodia formation through the regulation of EGF-induced diacylglycerol generation by PLCE1 and ARP2/3 complex assembly.
Synonyms: p92; FLJ12386; ADVIL; DOC6; NPHS21
Tractability: No criterion of Open Targets' tractability assessment is met for any kind of drug.
Gene: Protein-coding gene on chromosome 12 (57,797,376 to 57,818,734, reverse strand). Ensembl gene ENSG00000135407.
Subcellular location: Cytoplasm, cytoskeleton; Cell projection, lamellipodium; Cell junction, focal adhesion; Cell projection, neuron projection; Cell projection, axon
Gene Ontology:
Molecular function: actin filament binding; Arp2/3 complex binding; protein binding; actin binding; phosphatidylinositol-4,5-bisphosphate binding
Biological process: actin filament organization; cilium assembly; positive regulation of lamellipodium assembly; regulation of diacylglycerol biosynthetic process; actin filament severing; actin polymerization or depolymerization; barbed-end actin filament capping; nervous system development; positive regulation of neuron projection development; cytoskeleton organization; positive regulation of cellular component biogenesis; positive regulation of lamellipodium organization
Cellular component: actin filament; focal adhesion; lamellipodium; actin cytoskeleton; cell projection; neuron projection; axon; cytoskeleton
Genetic constraint (gnomAD): Loss-of-function variants: 76 observed, 113.58 expected, observed/expected ratio (o/e) 0.67, 90% interval 0.56 to 0.81. The upper end of that interval is the gene's LOEUF score, 0.81, which puts it in group 3 of 6, group 1 being the genes least tolerant of losing a copy. Missense variants: 886 observed, 1,067.6 expected, observed/expected ratio (o/e) 0.83, 90% interval 0.78 to 0.88. Synonymous variants: 366 observed, 398.65 expected, observed/expected ratio (o/e) 0.92, 90% interval 0.84 to 1.
Homologues: Orthologues: chimpanzee AVIL (99% identical), macaque AVIL (97% identical), pig AVIL (92% identical), dog AVIL (90% identical), rat Avil (90% identical), mouse Avil (89% identical), rabbit AVIL (88% identical), guinea pig AVIL (84% identical), tropical clawed frog avil (72% identical), zebrafish avil (63% identical), Drosophila melanogaster Gel (32% identical), Caenorhabditis elegans gsnl-1 (23% identical). Paralogues in human: VIL1 (61% identical), VILL (47% identical), SCIN (42% identical), GSN (42% identical), SVIL (29% identical), FLII (28% identical), CAPG (18% identical).
Diseases named in the same sentence as AVIL in open-access papers:
AVIL is named in the same sentence as 20 diseases in open-access papers, as found by Europe PMC text mining. Sharing a sentence is not in itself a finding about the gene and the disease. The quoted sentences say what the papers report.
glioblastoma (7 papers, 2020 to 2023). The most malignant astrocytic tumor (WHO grade IV). "When AVIL is silenced in culture, glioblastoma cells are almost eliminated, and silencing of AVIL in in vivo xenografts in mice inhibits these glioblastoma cells." (PMID 34065872, 2021). "We found that the AVIL locus is amplified in 15–18% of glioblastoma cases in The Cancer Genome Atlas (TCGA) studies via cBioPortal analysis." (PMID 32651364, 2020). "Here, the authors show that AVIL, an actin regulatory protein, is overexpressed in glioblastomas and mediates oncogenic effects through regulation of FOXM1 stability and LIN28B expression." (PMID 32651364, 2020). "We expressed Myc-tagged AVIL, either wild-type or mutants, in glioblastoma cells in which endogenous AVIL was silenced and performed co-immunoprecipitation with anti-Myc antibody to assess the interaction between actin and AVIL mutants." (PMID 32651364, 2020). "We found that advillin (AVIL) is overexpressed in all the glioblastomas we tested including glioblastoma stem/initiating cells, but hardly detectable in non-neoplastic astrocytes, neural stem cells or normal brain." (PMID 32651364, 2020). "A possible explanation for the IDH1 R132H mutation effect on cell culture nanomechanics is that it may be an effect of AVIL protein, which is upregulated in high-grade glioblastoma, especially the IDH1 wild-type." (PMID 36835465, 2023). "AVIL expression is increased in glioblastoma cells and glioblastoma stem or initiating cells." (PMID 34065872, 2021). "Therefore, AVIL seems to be a viable therapeutic target in glioblastoma and RMS." (PMID 37762498, 2023). "The AVIL locus is amplified in two glioblastoma cell lines, SF767 and A172, but not in three other glioblastoma lines, U87, U251, T98G, or in an immortalized astrocyte culture." (PMID 32651364, 2020). "In our own collection of eight non-tumor brain tissues, and 36 glioblastoma cases, we also confirmed the significant difference in AVIL RNA expression levels between the two groups." (PMID 32651364, 2020). "Our study shows that AVIL is overexpressed in the vast majority, if not all of human glioblastomas." (PMID 32651364, 2020).
glioma (4 papers, 2020 to 2025). A benign or malignant brain and spinal cord tumor that arises from glial cells (astrocytes, oligodendrocytes, ependymal cells). "AVIL overexpression promotes glioma cell proliferation and migration by regulating FOXM1 and LIN28B." (PMID 39964147, 2025).
rhabdomyosarcoma (2 papers, 2020 to 2023). A rare aggressive malignant mesenchymal neoplasm arising from skeletal muscle. "While studying a pediatric cancer, rhabdomyosarcoma, we discovered a gene fusion, which results in the juxtaposition of a house-keeping gene next to the AVIL gene." (PMID 32651364, 2020). "We suspected that fusion to MARS in rhabdomyosarcoma is one mechanism to misregulate AVIL gene expression, and that AVIL may be misregulated by other mechanisms in other cancers." (PMID 32651364, 2020).
autoimmune disorders (1 paper, 2023). "Chromosome 12 signal, rs2470341, is intergenic and located near the AVIL-TSFM-CYP27B1-TSPAN31 locus, which is gene-dense and previously been implicated with multiple distinct autoimmune disorders." (PMID 37666928, 2023).
endometrial cancer (1 paper, 2025). Primary or metastatic malignant neoplasm involving the endometrium (mucous membrane that lines the endometrial cavity). "We have identified the expression levels of GSN, CAPG, AVIL, SVIL, and FLII as independent survival risk factors in endometrial cancer (EC) patients." (PMID 39964147, 2025). "The low expression of CAPG, AVIL, and SVIL, together with the high expression of GSN, VILL, and FLII, were found to be significantly associated with poor overall survival in endometrial cancer patients." (PMID 39964147, 2025).
influenza (1 paper, 2023). An acute viral infection of the respiratory tract, occurring in isolated cases, in epidemics, or in pandemics; it is caused by serologically different strains of viruses (influenzaviruses) designated A, B, and C, has a 3-day incubation period, and usually lasts for 3 to 10 days. "We then crossed Ptger3flox mice with either Nestin-cre or Advillin-creER mice, which target Cre recombinase to most central or peripheral neurons, respectively, and measured influenza-induced sickness behaviours." (PMID 36890237, 2023). "Influenza-induced decreases in feeding, drinking, movement, body weight and survival were attenuated in Advillin-creER; Ptger3flox mice, with effect magnitudes similar to ibuprofen treatment, but persisted in Nestin-cre; Ptger3flox mice." (PMID 36890237, 2023). "Influenza infection induced PGE2 to similar levels in plasma and BALF of Gabra1-IRES-cre; Ptger3flox, Phox2b-cre; Ptger3flox, Advillin-creER; Ptger3flox and Ptger3flox mice, consistent with changes in PGE2 detection rather than PGE2 synthesis underlying the observed behavioural differences." (PMID 36890237, 2023). "Advillin-creER; Ptger3flox mice were treated with tamoxifen to induce Cre-mediated recombination at least one week before virus administration; prior tamoxifen treatment of control mice did not affect the subsequent behavioural responses to influenza infection." (PMID 36890237, 2023).
liver cancer (1 paper, 2024). An epithelial or non-epithelial malignant neoplasm that arises from the liver. "We identified YWHAE as significantly associated with liver fibrosis, AVIL, FIS1, MUC1, ACOT7, CLUH, HNF4A, and TNFSF10 with liver cancer, and AVIL with liver disease-related mortality (FDR-adjusted P values < 0.05)." (PMID 38862964, 2024).
cancer (7 papers, 2020 to 2025). A tumor composed of atypical neoplastic, often pleomorphic cells that invade other tissues. "This selective overexpression of AVIL in RMS makes cancer cells vulnerable to targeting of the cytoskeleton while sparing actively dividing but healthy cells." (PMID 37762498, 2023). "Conversely, CAPG, AVIL, and SVIL expression negatively correlated with anticancer immune cells and positively correlated with immunosuppressive cells like TAMs, Tregs, Th2 cells, MDSCs, and cancer‐associated fibroblasts (CAFs)." (PMID 39964147, 2025). "This dysregulated signaling may lead to disrupted advillin function in cancer, allowing for promotion and metastasis of GBM." (PMID 34948433, 2021). "While the exact regulation mechanisms of the advillin are still under investigation, it and similar proteins from its family could be intricately involved in the formation of our most deadly cancers." (PMID 34948433, 2021). "Suspecting that other tumors may also dysregulate AVIL expression, we examined AVIL in adult cancers and found its critical role in the tumorigenesis of GBM." (PMID 32651364, 2020). "Advillin may be a relatively cancer-specific cytoskeletal protein that sits at the crossroads of the two therapeutic philosophies: broad range cytotoxic agents that target machinery required for division and a cancer-specific targeted therapy that limits toxicities in normal cells." (PMID 34948433, 2021). "Given its differential overexpression in numerous cancers including RMS, and its ability to activate both RAS and PAX3–FOXO1 signaling pathways, AVIL demonstrates promising therapeutic potential as a target for both ERMS and ARMS." (PMID 37762498, 2023). "AVIL appears to be a relatively cancer-specific cytoskeletal protein overexpressed in RMS, a pediatric cancer with limited treatment options." (PMID 37762498, 2023). "Recently, our lab discovered a previously seen but relatively uncharacterized oncogenic actin-binding protein, advillin (AVIL), to be upregulated in GBMs as well as other cancers." (PMID 34948433, 2021). "AVIL, as a novel oncogene gene in LGG, was reported to play important roles in functions of cancer in vivo or in vitro through literature searches." (PMID 34163522, 2021). "Due to its key role in the organization of the actin cytoskeleton, which affects polarity, movement, cell division, and trafficking, it is not surprising that advillin appears to play a role in many cancers." (PMID 37762498, 2023). "In this perspective paper, we will explain why AVIL, an actin-binding protein recently found to be overexpressed in GBM and a driving force for GBM, could prove versatile in the fight against cancer." (PMID 34948433, 2021). "All tuft cell-like cancers identified in this way also strongly expressed other tuft cell-markers, such as TRPM5, SOX9, ASCL2, and AVIL but not CHAT." (PMID 36402755, 2022).
tumor (6 papers, 2012 to 2024). "This indicates that loss of AVIL function inhibits the tumor’s ability to escape some tumor-suppressing mechanisms via apoptosis." (PMID 34948433, 2021). "This could indicate that the loss of AVIL function can interrupt the tumor’s ability to invade neighboring brain tissue." (PMID 34948433, 2021). "Downstream of AVIL, FOXM1 is implicated in angiogenesis, tumor invasion, and EMT, while LIN28B allows expression of oncogenes by inhibiting let-7 miRNAs." (PMID 34948433, 2021). "Two different microarray probes showed that AVIL expression correlates with tumor grade, with the highest levels in GBMs." (PMID 32651364, 2020). "With its versatile function, it could be hypothesized that AVIL can carry out the functions of other gelsolin/villin family proteins in tumor cells." (PMID 34948433, 2021). "To confirm whether AVIL plays an important role in tumorigenesis in vivo, we tested the effect of silencing AVIL in tumor initiation with a widely used U251 intracranial xenograft model." (PMID 32651364, 2020). "Indeed, the cells from AVIL overexpressed astrocytes revealed a neoplasm with histologic features of malignancy including necrosis (N), frequent mitotic figures (arrows), and apoptotic figures (asterisks)." (PMID 32651364, 2020). "We then examined the AVIL protein in 12 non-tumor brain tissues, and 14 GBMs." (PMID 32651364, 2020). "The hypothesized pro-tumor roles of AVIL specifically through the FOXM1/LIN28B axis is seen in." (PMID 34948433, 2021). "AVIL’s overexpression in tumor cells and lack of expression in noncancerous tissue is promising by itself." (PMID 34948433, 2021). "Actin affects tumor mobility, metastasis, and invasion, and treatments targeting AVIL would be able to target the cytoskeleton without affecting tubulin, thus avoiding some deleterious effects in noncancerous dividing cells throughout the body." (PMID 34948433, 2021). "The AVIL protein was absent, or barely detected in the non-tumor cases, but higher levels of AVIL protein expression were seen in almost all of the GBM cases." (PMID 32651364, 2020).
kidney disease (1 paper, 2020). "Proteins anillin, coded on the ANLN gene, and advillin, coded on AVIL gene, are both F-actin-binding proteins needed for podocyte motility and both have mutations that are associated with kidney disease." (PMID 32708597, 2020).
peripheral neuropathy (1 paper, 2022). A disorder affecting the peripheral nervous system. "Thus, inhibition of KCNQ channel activity alone in adult rats induced PIPN-like peripheral neuropathy, yet Advillin-Cre-induced KCNQ2cko displayed unaltered pain threshold." (PMID 36552832, 2022).
AVIL also shares sentences with these, for which no sentence is quoted: adenoma (1 paper); astrocytomas (1); colon cancer (1); gastric cancer (1); liver disease (1); liver fibrosis (1); neuroblastoma (1); oligodendroglioma (1); polyp (1).